C2CD4A (C2 calcium dependent domain containing 4A)
Description:
May be involved in inflammatory process. May regulate cell architecture and adhesion.
Synonyms: FAM148A; NLF1
Tractability: No criterion of Open Targets' tractability assessment is met for any kind of drug.
Gene: Protein-coding gene on chromosome 15 (62,066,977 to 62,070,917, forward strand). Ensembl gene ENSG00000198535.
Subcellular location: Nucleus
Subcellular location (Human Protein Atlas): Nucleoplasm; Nucleoli
Gene Ontology:
Biological process: positive regulation of acute inflammatory response; regulation of cell adhesion; regulation of vascular permeability involved in acute inflammatory response
Cellular component: nucleolus; nucleoplasm; nucleus
Genetic constraint (gnomAD): Loss-of-function variants: 3 observed, 0.83 expected, observed/expected ratio (o/e) 3.61. That is too few expected variants to judge how well the gene tolerates losing a copy. Missense variants: 610 observed, 396.65 expected, observed/expected ratio (o/e) 1.54, 90% interval 1.44 to 1.64. Synonymous variants: 297 observed, 180.07 expected, observed/expected ratio (o/e) 1.65, 90% interval 1.5 to 1.82.
Homologues: Orthologues: macaque C2CD4A (90% identical), chimpanzee C2CD4A (89% identical). Paralogues in human: C2CD4B (80% identical), C2CD4C (32% identical), C2CD4D (28% identical), SYTL1 (16% identical), SYT5 (14% identical), SYTL3 (14% identical), SYTL5 (14% identical), RPH3A (14% identical), SYT15 (14% identical), SYT15B (14% identical), SYTL4 (14% identical), SYT11 (14% identical), and 19 more.
Diseases named in the same sentence as C2CD4A in open-access papers:
C2CD4A is named in the same sentence as 6 diseases in open-access papers, as found by Europe PMC text mining. Sharing a sentence is not in itself a finding about the gene and the disease. The quoted sentences say what the papers report.
type 2 diabetes (2 papers, 2011 to 2025). "Similarly, transcripts of candidate genes for type 2 diabetes (Blk, C2cd4a, C2cd4b, Cdkn2a, Hnf1a, Mtnr1b, Pou5f1, Slc30a8) and type 1 diabetes (Cd69, Il2, IL27) were not expressed in the brain." (PMID 39920851, 2025). "Three Japanese GWAS including ours, have identified the association of the potassium voltage-gated channel KQT-like subfamily member 1 (KCNQ1) locus, ubiquitin-conjugating enzyme E2E 2 (UBE2E2) locus and C2 calcium-dependent domain containing 4A (C2CD4A)-C2CD4B locus with type 2 diabetes." (PMID 22046406, 2011).
diabetes (1 paper, 2021). "C2cd4a and C2cd4b were both upregulated in pancreatic islets of high-fat-diet--fed DBA2J mouse model of diabetes following 30 and 90 days of the diet vs RC-fed mice." (PMID 33492421, 2021).
pituitary adenomas (1 paper, 2023). "The expression levels of ANXA2, PMAIP1, SPRY2, C2CD4A, APOD, FGF14 and FKBP10 were significantly upregulated while FNDC5 and MAP3K4 were downregulated in the invasive gonadotrophic pituitary adenomas compared to the non-invasive ones." (PMID 36750863, 2023).
gastrointestinal tumors (1 paper, 2021). "Based on our previous studies on miRNAs in gastrointestinal tumors, it was aimed to further figure out whether the overexpression of C2CD4A in CRC was caused by a specific miRNAs dysregulation." (PMID 34656159, 2021).
C2CD4A also shares sentences with these, for which no sentence is quoted: mastitis (1 paper); type 1 diabetes (1).